CYP1B1 (cytochrome P450 family 1 subfamily B member 1)
Diseases named in the same sentence as CYP1B1 in open-access papers (continued):
Sharing a sentence is not in itself a finding about the gene and the disease.
primary congenital glaucoma (continued). "Studies of pathogenic sequence variants in CYP1B1 will contribute to better understanding of primary congenital glaucoma." (PMID 18989382, 2008). "The gene coding cytochrome P4501B1 (CYP1B1) has been shown to be a major cause of primary congenital glaucoma in the Iranian population." (PMID 19096718, 2008). "First, CYP1B1 functions as the dominant causal gene across both primary congenital glaucoma (PCG) and juvenile-onset open-angle glaucoma (JOAG), accounting for 76-86% of cases, with two founder alleles, p.G61E (penetrance 87.7%) and p.R469W (penetrance 93%), driving severe, early-onset phenotypes." (PMID 42074148, 2026). "Variants in the CYP1B1 gene are most commonly associated with primary congenital glaucoma (PCG) but have also been identified in other congenital eye diseases, such as congenital ectropion uvea (CEU), congenital corneal opacification (CCO), Axenfeld–Rieger Syndrome (ARS), sclerocornea, and aniridia." (PMID 40141740, 2025). "Mutations in CYP1B1 are associated with the development of primary congenital glaucoma in humans." (PMID 36230892, 2022). "CYP1B1 loss of function (LoF) is the main known genetic alteration present in recessive primary congenital glaucoma (PCG), an infrequent disease characterized by delayed embryonic development of the ocular iridocorneal angle; however, the underlying molecular mechanisms are poorly understood." (PMID 34208498, 2021). "Rashid M., Yousaf S., Sheikh S.A., Sajid Z., Shabbir A.S., Kausar T., Tariq N., Usman M., Shaikh R.S., Ali M., Bukhari S.A.,Waryah A.M., Qasim M., Riazuddin S., Ahmed Z.M. Identities andfrequencies of variants in CYP1B1 causing primary congenital glaucoma in Pakistan." (PMID 35087999, 2020). "Sarfarazi M. Targeted screening for predominant CYP1B1 mutationsin primary congenital glaucoma." (PMID 35087999, 2020). "Chavarria-Soley G., Michels-Rautenstrauss K., Pasutto F., Flikier D.,Flikier P., Cirak S., Bejjani B., Winters D.L., Lewis R.A., Mardin C.,Reis A., Rautenstrauss B. Primary congenital glaucoma and Rieger’sanomaly: extended haplotypes reveal founder effects for eight distinct CYP1B1 mutations." (PMID 35087999, 2020). "CYP1B1 is the most commonly mutated gene in primary congenital glaucoma (PCG)." (PMID 25261878, 2014). "In 1997, CYP1B1 was first identified as a causal gene for primary congenital glaucoma (PCG)." (PMID 23028769, 2012). "Mutations in the CYP1B1 gene are a frequent cause of primary congenital glaucoma." (PMID 19754948, 2009). "CYP1B1 mutations associated with primary congenital glaucoma in Omani patients." (PMID 19597567, 2009). "Human CYP1B1 has been implicated in primary congenital glaucoma in different human populations." (PMID 19234632, 2009). "Interestingly, this haplotype has been reported to harbor a vast majority of the CYP1B1 mutations causal to primary congenital glaucoma (PCG) across different population groups worldwide." (PMID 18483560, 2008). "Defects in cytochrome P450 1B1 (CYP1B1) cause primary congenital glaucoma." (PMID 18483560, 2008). "Defects in CYP1B1 cause an autosomal recessive form of primary congenital glaucoma (PCG)." (PMID 18483560, 2008). "In addition, heterozygous mutations in cytochrome P450 1B1 CYP1B1, a gene involved in primary congenital glaucoma, have been identified in 4-9% of affected POAG subjects from France, India, and Spain." (PMID 17615537, 2007). "Thus, altered iron homeostasis in response to Cyp1b1-deficiency may significantly impact tissue redox homeostasis and developmental processes linked to Cyp1b1 expression including the trabecular meshwork and pathogenesis of primary congenital glaucoma." (PMID 30372497, 2018). "Our research demonstrates a complex interplay between the ordered and disordered regions of the CYP1B1 protein, which is crucial for understanding its multifaceted role in primary congenital glaucoma (PCG)." (PMID 40821877, 2025).
primary congenital glaucoma (continued). "Cytochrome P450 1B1 (CYP1B1) plays a critical role in the pathogenesis of primary congenital glaucoma (PCG), a severe eye disorder that can lead to pediatric blindness if untreated." (PMID 40821877, 2025). "Among the two causative genes (CYP1B1 and LTBP2) of primary congenital glaucoma (PCG), CYP1B1 is found to be highly mutated and responsible for the etiology of PCG patients worldwide." (PMID 36518267, 2022). "Remarkably, CYP1B1 is known as the most frequent causative gene in primary congenital glaucoma and its mutations were often found in POAG patients suggesting the existence of a common CYP1B1-mediated mechanism of both variants of the disease." (PMID 34356513, 2021). "With this, the role of cytochrome CYP1B1 was confirmed in primary congenital glaucoma, as it influenced the development of the trabecular meshwork; CYP1B1 is also a potential regulator in energy homeostasis that promotes hypertension as well." (PMID 32168880, 2020). "One study showed that CYP1B1−/− mice exhibited structural abnormalities in the ocular drainage structures, similar to human primary congenital glaucoma (PCG)." (PMID 22509109, 2012). "CYP1B1 (OMIM 601771), encoding cytochrome P4501B1, is a gene commonly associated with primary congenital glaucoma (PCG; OMIM 231300); however, mutations in CYP1B1 have been reported in JOAG patients." (PMID 18385784, 2008). "CYP1B1 (OMIM 601771), encoding cytochrome P4501B1, is a gene commonly associated with primary congenital glaucoma." (PMID 19096718, 2008). "Axenfeld–Rieger syndrome and primary congenital glaucoma share some causative genes (FOXC1 and CYP1B1) that may also induce other subtypes of ASD (aniridia, iris hypoplasia, and Peters anomaly), while the LTBP2 gene is confined to primary congenital glaucoma." (PMID 40364033, 2025). "The most common phenotype disease in humans with CYP1B1 mutations is primary congenital glaucoma, but the studies in these individuals have not investigated changes in neurosteroids." (PMID 37442234, 2023). "Furthermore, CYP1B1, which is responsible for metabolizing 17β-estradiol, is associated with POAG as well as primary congenital glaucoma." (PMID 34638643, 2021). "CYP1B1 and MYOC are genetic etiologies for primary congenital glaucoma (PCG) and juvenile open-angle glaucoma (JOAG), respectively, tested by four of the four panels." (PMID 36981008, 2023). "Clinical data including CYP1B1 and MYOC sequencing results of subjects with primary congenital glaucoma." (PMID 22219654, 2011). "Regarding the physiological function of the Cyp1b1 enzyme, Cyp1b1-/- mice exhibit no apparent abnormalities except in their anterior eye segment similar to what has been reported for patients with primary congenital glaucoma." (PMID 21867498, 2011). "However, it should not be forgotten that primary congenital glaucoma is not peculiar to the CYP1B1 gene." (PMID 36239105, 2022).
prostate carcinoma (44 papers, 2003 to 2025). A carcinoma that arises from epithelial cells of the prostate gland. "Unconventional steroid metabolism pathways driven by CYP1B1 are implicated in prostate cancer malignancy." (PMID 38534761, 2024). "Pathways identified in enrichment and network analysis of CYP1B1 align with its role in activating pathways associated with drug resistance in prostate cancer." (PMID 38534761, 2024). "In vivo study indicated that vitamin E upregulated CYPs, including CYP1A1 and CYP1B1 which highly expressed in prostate cancer, increased ROS production and led to the mutation of prostate cells." (PMID 33230422, 2020). "As genotypes and haplotypes were observed to be a risk for prostate cancer, expression level of CYP1B1 protein was evaluated for all sites." (PMID 30133114, 2018). "The authors showed that p.Leu432Val CC homozygote was significantly associated with higher expression levels of CYP1B1 mRNA in biochemical recurrence in prostate cancer patients." (PMID 29507678, 2018). "When evaluating polymorphic sites of CYP1B1, the minor allele at rs2551188, rs2567206 and rs10175368 were an overall risk for prostate cancer." (PMID 30133114, 2018). "The present study evaluated the risks of CYP1B1 polymorphisms in the promoter region/5′UTR for prostate cancer and the influence of lifestyle factors in a Caucasian population." (PMID 30133114, 2018). "In conclusion, polymorphisms of the promoter and 5′UTR region of CYP1B1 are determined to be a risk for prostate cancer that can be modified by lifestyle factors in Caucasian men." (PMID 30133114, 2018). "As lifestyle factors can affect risks of prostate cancer, interaction between choices and CYP1B1 polymorphisms were determined." (PMID 30133114, 2018). "The association of the rs1056836 (CYP1B1) polymorphism with the risk of prostate cancer has been intensively investigated in Caucasian and Japanese populations." (PMID 27074016, 2016). "CYP1B1 Val genotype is associated with lower response rate, shorter progression-free-survival and decrease overall survival in breast and prostate cancer patients treated with taxanes based chemotherapy." (PMID 26180747, 2015). "The importance of CYP1B1 in chemical carcinogens is well illustrated in animal models in which metabolites of CYP1B1 were shown to induce Prostate cancer risk." (PMID 25115775, 2014). "In particular, estrogen exposure has been implicated in the disease aetiology of prostate cancer, and CYP1B1 is up-regulated in prostate cancer." (PMID 20875115, 2010). "This is the first study that systematically evaluates the influence of multiple genetic variants in the CYP1B1 gene on prostate cancer risk using a haplotype approach." (PMID 14562027, 2003). "In this study, we tested for an association between polymorphisms in the CYP1B1gene and prostate cancer risk by comparing the allele, genotype, and haplotype frequencies of CYP1B1 SNPs among HPC probands, sporadic prostate cancer cases, and unaffected men." (PMID 14562027, 2003). "In this study, we comprehensively studied the genetic variants of CYP1B1 and the risk to prostate cancer, providing preliminary evidence for an association between CYP1B1 haplotype and the risk to prostate cancer." (PMID 14562027, 2003). "Furthermore, high expression of CYP1B1 has been implicated in the resistance of prostate cancer cells to docetaxel." (PMID 38534761, 2024). "Patient 1 presented the LP variant CYP1B1 c.1159G > A. The protein encoded by CYP1B1 plays a role in the metabolism of steroid hormones and the progression of certain cancers, such as breast and prostate cancer." (PMID 37628631, 2023). "Lifestyle choices can therefore modify the risks of CYP1B1 polymorphisms for prostate cancer." (PMID 30133114, 2018). "Polymorphic variants of CYP1B1 altering the catabolism of estrogen may modify prostate cancer risk and may also predict response to chemotherapy." (PMID 28388569, 2017).
prostate carcinoma (continued). "CYP1B1 overexpression decreased sensitivity to docetaxel in vitro and its polymorphic allele leading both increased expression and activity is associated with poor response to taxanes in breast and prostate cancers." (PMID 25860934, 2015). "Additionally, CYP1B1*2 G355T and CYP1B1*3 C4326G have also been reported to be associated with susceptibility to hormone-related cancers such as prostate cancer, bladder cancer, and carcinoma of the endometrium." (PMID 25299224, 2014). "In addition, we hypothesise that polymorphisms in CYP1B1 impose a different risk for hereditary prostate cancer compared to sporadic prostate cancer." (PMID 14562027, 2003). "It is also the first report to include hereditary prostate cancer patients, which enabled us to test whether the degree of association between the polymorphisms of CYP1B1 and prostate cancer risk is strong enough to contribute to familial aggregation of prostate cancer." (PMID 14562027, 2003). "UA was shown to be an inhibitor of CYP1B1, and prolonged exposure to UA increased its inhibitory effects on 22Rv1 prostate cancer cells." (PMID 40568370, 2025). "The enzyme CYP1B1 played a crucial role in the advancement and progression of castration-resistant prostate cancer." (PMID 39494300, 2024). "CYP1B1 is abnormally highly expressed in various cancers in various cancers (e.g., breast, head and neck cancers and prostate cancer)." (PMID 37644041, 2023). "PROTAC 6C with a six-carbon linker chain induced the degradation of CYP1B1 and restored sensitivity to docetaxel in the prostate-cancer cells overexpressing CYP1B1 (DU145/CY)." (PMID 36986673, 2023). "Meanwhile, elevated CYP1B1 levels enhance the resistance of ovarian and prostate cancer cells to paclitaxel." (PMID 35292057, 2022). "High CYP1B1 expression is found in multiple malignant tumors, including those of the brain, breast, colon, ovarian, and prostate cancers 9,38." (PMID 32626511, 2020). "It would be of interest in the future to determine if overexpression or silencing of CYP1B1 affects eicosanoid levels in prostate cancer tissue and how individual eicosanoids affect caspase-1 expression and activity in vitro and in vivo." (PMID 32581794, 2020). "Hypomethylation in the promoter region of CYP1B1 regulates the overexpression of this gene, as determined in clinical prostate tissues and prostate cancer cell lines using methylation-specific PCR and bisulfite-modified DNA sequencing." (PMID 32626511, 2020). "Influence of lifestyle choices on frequencies of major haplotypes of rs2551188‐rs2567206‐rs2567207‐rs1017536 (G‐C‐T‐G) and rs163090‐rs162330‐rs162331 (A‐G‐A and T‐T‐G) of CYP1B1 between healthy controls and prostate cancer patients." (PMID 30133114, 2018). "In this report, we evaluated the risks of 8 polymorphic sites in the promoter region/5′UTR of CYP1B1 for prostate cancer and how this is influenced by major lifestyle factors among a Caucasian population." (PMID 30133114, 2018). "Despite its up-regulation in prostate cancer (PCa), biological significance and clinicopathological features of CYP1B1 are still elusive." (PMID 28388569, 2017). "Inhibition of AhR signaling by direct inhibitor, CH223191, resulted in a substantial decrease in CYP1B1 levels in the advanced prostate cancer cell lines." (PMID 24755659, 2014). "Distribution of CYP1B1 genotype among prostate cancer cases and controls included in the meta-analysis." (PMID 23861929, 2013). "The cytochrome P450 enzyme CYP1B1 plays a critical role in prostate cancer development." (PMID 40568370, 2025). "Overexpression of CYP1B1 has been documented in drug-resistant prostate cancer tumors." (PMID 38534761, 2024). "However, CYP1B1 is particularly overexpressed in hormone-related or estrogen-dependent cancers, such as breast, ovarian, and prostate cancers." (PMID 33185690, 2020).
prostate carcinoma (continued). "Cytochrome P450 1B1 (CYP1B1) converts xenobiotics to carcinogens and how lifestyle choices may interact with CYP1B1 polymorphisms and affect prostate cancer risk was assessed." (PMID 30133114, 2018). "CYP1B1 is overexpressed in a variety of human tumor cells including prostate cancer." (PMID 28388569, 2017). "We investigated whether functional polymorphisms of CYP17, CYP19, CYP1B1, COMT and UGT1A1 affected the risk of prostate cancer in two different populations of African ancestry." (PMID 27074016, 2016). "In prostate cancer cells, urolithins (A, B, C, and D) inhibited CYP1B1 activity (a target in prostate cancer chemoprevention) in a dose ranging from 1.15 μM (urolithin A) to 137 μM (urolithin D) whereas higher concentrations were needed for CYP1A1 activity inhibition (12.4–2,907 μM)." (PMID 23781257, 2013). "Tryptophan metabolism was one of the 27 pathways, and the downstream target genes of AhR, CYP1A1 and CYP1B1, were considerably elevated after AhR binding, suggesting that tryptophan metabolism is significantly activated in recurrent castration-resistant prostate cancer." (PMID 40759641, 2025). "AHR is expressed in prostate cancer cells and induces its known target genes CYP1A1 and CYP1B1." (PMID 37077937, 2023). "To date, studies on polymorphic variants of the CYP1B1 promoter region/5′UTR and their risks for prostate cancer and their functional role are lacking." (PMID 30133114, 2018). "To determine whether CYP1B1 expression is correlated with CASP1 level, we first examined the level of CASP1 in prostate cancer tissue samples." (PMID 28388569, 2017). "AhR responsive gene CYP1B1 is expressed in non-small cell lung cancer cells as well as prostate cancer cell lines in the absence of an exogenous ligand." (PMID 25068070, 2013). "To test these hypotheses, we estimated the frequencies and tested for differences in the frequencies of CYP1B1 SNPs among 159 HPC probands, 245 sporadic prostate cancer cases, and 211 unaffected men." (PMID 14562027, 2003). "Our data confirmed that the treatment of prostate cancer cells with ENZA enhances the effect of radiation through down-regulation of NKX3-1, ZMIZ1, SPDEF and PDE9A genes and up-regulation of LAT, PTPRN2 and OSBPL10 genes in LNCaP cells, as well as up-regulation of CYP1B1 genes in C4-2 cells." (PMID 31221986, 2019). "CYP1B1 expression was examined in human prostate cell lines, which included a non-tumorigenic prostate epithelial cell line (RWPE-1) and prostate carcinoma cell lines (LNCaP, PC-3 and DU145)." (PMID 28388569, 2017).